IDH1 (isocitrate dehydrogenase (NADP(+)) 1)
Diseases named in the same sentence as IDH1 in open-access papers (continued):
Sharing a sentence is not in itself a finding about the gene and the disease.
cancer (continued). "IDH mutation-induced 2HG regulates DNA and histone methylation Two independent groups undertaking cancer genome sequencing projects identified IDH1 mutations in both glioblastoma multiforme and acute myeloid leukemia in 2008 and 2009, respectively." (PMID 34050894, 2022). "We construct computational models of glucose and glutamine metabolism with focus on the effect of IDH1/2-mutations in cancer using a combination of experimental metabolic flux data and patient-derived gene expression data." (PMID 36344581, 2022). "Several researches have suggested that the potential cancer-specific mutated driver genes include IDH1/2 and H3 histone (H3F3A)." (PMID 36181110, 2022). "With respect to the TME, there are conflicting reports as to the effect of IDH1/2 mutation in cancer cells on the ECs, showing both increased and reduced pro-angiogenic signaling." (PMID 36582801, 2022). "IDH1 was the top mutated gene in both low- and high-immunity groups and has been previously identified to be involved in tumorigenesis and cancer progression." (PMID 36275718, 2022). "IDH1 mutations occur in a variety of cancers, and further insight into their effects on cellular processes — including metabolism in particular cancer entities — is an important area of development." (PMID 34941573, 2022). "In these cancers, IDH1 and IDH2 variants are thought to alter the catalytic function of the mutant enzymes, leading to the production of the oncometabolite D-2-hydroxyglutarate (D-2HG) from α-ketoglutarate (α-KG)." (PMID 36480544, 2022). "Among the 19 CIMP-positive cancers, very few shared potential driver events, and those drivers were only IDH1 and SETD2 mutations." (PMID 35134107, 2022). "This provided a platform for the design of structure-based inhibitors targeting IDH1 mutated cancers in more depth." (PMID 35402370, 2022). "A large number of studies have found that IDH1 mutations are associated with the occurrence and development of various cancers." (PMID 36091829, 2022). "IDH1 mutations are not only the common single genetic incidents in cancer but are also associated with more invasive diseases and better patient prognosis in numerous cancers, particularly GBM." (PMID 35669882, 2022). "These inhibitors decrease the stemness of the targeted IDH1/2-mutated cancer cells and induce their differentiation to more mature cells." (PMID 34967233, 2022). "During the early preclinical investigation of the biological effects of mtIDH1/2 and their inhibitors, the increased stemness of IDH1/2mt cancer cells and its underlying mechanisms were already appreciated." (PMID 34967233, 2022). "For example, some reports have suggested that disease progression in iCCAs receiving the IDH1 inhibitor ivosidenib was associated with the induction of PD-L1 in cancer cells, Treg recruitment, and higher PD-1, CTLA-4, and CD80 expression in the TME." (PMID 36142781, 2022). "This cell line was derived from fibrosarcoma, but mutations in the IDH1 gene are characteristic for several other cancer types, such as central nervous system (CNS) tumors or acute lymphoblastic leukemia (the most common one)." (PMID 35342397, 2022). "IDH mutations linked to cancer are most commonly found in the arginine residue, which is required for isocitrate recognition (R132 for IDH1, R140, or R172 for IDH2)." (PMID 35769466, 2022). "In vitro studies have demonstrated that employing NAMPT inhibitors to treat cancer cells, particularly cancer cell lines with IDH1/2 mutations, is considerably effective." (PMID 36160449, 2022). "The compound (T001-0657) showed the most potent effect against cancer cells harboring the IDH1-R132C mutation with a half-maximal inhibitory concentration (IC50) value of 1.311 μM." (PMID 36160383, 2022). "The most common cancer mutations involve the IDH1 and IDH2 isoforms and resulted to be mutually exclusive." (PMID 34070384, 2021).
cancer (continued). "Cancer-associated mutations have been identified in two of the three existing isoforms: IDH1 and IDH2, which are mutually exclusive." (PMID 36045702, 2021). "Isocitrate dehydrogenase 1 and 2 (IDH1/2) mutations and their key effector 2-hydroxyglutarate (2-HG) have been reported to promote oncogenesis in various human cancers." (PMID 34516556, 2021). "The isocitrate dehydrogenase 1 (IDH1) gene is an example that is known to frequently mutate in different types of cancer and influence EGFR expression." (PMID 33419230, 2021). "In this study, we expressed cancer-associated hotspot IDH1/2 mutants in MEF cells or HCT116 cells and performed functional analysis." (PMID 34516556, 2021). "IDH1 mutations appear to be important also in IBD-CRCs where sporadic cancer gene mutations occur less often." (PMID 34880756, 2021). "In the remaining cancer types in which IDH1 or IDH2 mutations are reported, the incidence rates are lower (<5%)." (PMID 35028610, 2021). "Cancer-associated IDH1 mutations produce R(−)-2-hydroxyglutarate (2HG) instead of α-ketoglutarate, the latter altering cancer metabolism and creating oxidative stress." (PMID 34638714, 2021). "It has been shown that IDH1 mutations sensitize cancer cells in vitro to therapies that involve oxidative stress, such as radiotherapy, cisplatin and carmustine." (PMID 34069550, 2021). "Molecular targeting of IDH1/2 mutant enzyme has long been pursued as a novel therapeutic approach to control the progression of IDH1/2 mutated cancers." (PMID 34571995, 2021). "Collectively, these results strongly illustrate that combinatorial therapy is of great interest to rescue TET activity and treat IDH1/2-mutated cancers." (PMID 34425876, 2021). "Together, these results suggest that Glut1 is a potential target regulated by cancer-associated IDH1/2 mutations." (PMID 34516556, 2021). "Triptolide is a potent Nrf2 inhibitor that can inhibit the transcriptional activity of Nrf2, leading to the apoptosis of isocitrate dehydrogenase (IDH)-mutant cells, providing an operable strategy for the treatment of malignant tumors with IDH1 mutations." (PMID 34158845, 2021). "Although the involvement of IDH1/2 mutations in cancer has been reported, the precise mechanism(s) of mutant IDH1/2 in carcinogenesis remains to be elucidated." (PMID 34516556, 2021). "The metabolism of IDH1-mutated cancer cells is reprogrammed in order to produce the oncometabolite D-2-hydroxyglutarate (D-2HG)." (PMID 34069550, 2021). "IDH1-mutated cancer cells are more vulnerable to inhibition of metabolism with inhibitors of the electron transport chain (ETC), such as metformin that inhibits complex I of the ETC." (PMID 34069550, 2021). "Mutant IDH1 induces changes in lipid metabolites and cancer cells with IDH1 mutation are more dependent on citrate and FA under hypoxia." (PMID 33923299, 2021). "Cancer-associated mutations typically involve heterozygous mutations within the active sites of IDH1 (IDH1)R132H and mitochondrial IDH2 (IDH2)R140Q and (IDH2)R172K." (PMID 33572577, 2021). "Robust and selective inhibition of IDH1/2 variants, resulting in reduced 2HG levels, has been demonstrated and is being explored as a new avenue in cancer therapy." (PMID 34854890, 2021). "AG-120 (Ivosidenib), an optimized compound from AGI-5198, is an FDA-approved oral administration drug that can effectively reduce the intracellular D-2-HG and induce IDH1 R132H and IDH1 R132C mutated cancer cell differentiation in AML murine xenograft models." (PMID 34571995, 2021). "IDH1 mutations are known to play a role in affecting cancer metabolism and have been validated as the most significant biomarker for predicting a longer overall survival time in LGG patients." (PMID 34439934, 2021). "In this study, Glut1 was identified as a downstream target molecule induced by the cancer-associated hotspot IDH1/2 mutants through a PI3K/Akt/mTORC1-Hif1α axis." (PMID 34516556, 2021).
cancer (continued). "Cancer-related IDH1 and IDH2 mutations occur almost entirely on different arginine residues at the active site of the enzyme." (PMID 33981605, 2021). "In vitro, we previously showed that IDH1-mutated cancer cells are more sensitive to metformin compared to IDH1 wild-type cancer cells." (PMID 34069550, 2021). "Using multiple logistic regression correcting for gender, race, and cancer type, mutations in IDH1 (OR = 0.9608, 95% CI = 0.9497–0.9719, adj." (PMID 33879792, 2021). "In cancer, increases in 2-hydroxyglutarate arise through mutations in IDH1 but can also increase physiologically with hypoxia and shifts to acidic pH." (PMID 34822384, 2021). "GSK864 and AGI-6780 are small molecules that selectively inhibit the cancer-associated mutants of IDH1 and IDH2/R140Q, respectively." (PMID 34876568, 2021). "Deep valleys followed by the highest growth peaks corresponded with close approximation to the three missense mutations from known cancer genes (IDH1, IDH2, and FLT3, p value < 2.2e−16)." (PMID 32024824, 2020). "Although we recorded Rac1-guided cellular motility in IDH1-mutated cells, a key question remains elusive with regards to how Rac1 is regulated in this type of cancer." (PMID 32224866, 2020). "On the other hand, mutations of the genes encoding the IDH1 enzyme have also been found in several cancers, mainly in about 80% of low-grade gliomas and secondary GBMs, about 40% of T cell lymphomas and in about of 10% of myeloid leukemias." (PMID 32110969, 2020). "In contrast, the examination of potential IDH1 alterations in 161 MSS CRCs revealed four cancers with IDH1 mutation, which were all CIMP-positive and BRAF mutant." (PMID 32610612, 2020). "One recent example is the discovery of AG−120 (ivosidenib), a highly specific, allosteric, reversible inhibitor of the isocitrate dehydrogenase−1 (IDH1) mutant enzyme (a mutation present in several types of cancer)." (PMID 32751973, 2020). "This study demonstrates the first example of IDH1 R132H mosaicism, acquired during early development, that provides an alternative mechanism of cancer predisposition." (PMID 32010615, 2020). "Five mutations have been described (i.e., p.R132H, p.R132C, p.R132G, p.R132S, and p.R132L) in IDH1-mutated cancers, but R132C is the most frequent in iCCA." (PMID 32824685, 2020). "As previously reported, iCCA is one of the cancer types that frequently harbors mutations in the IDH1 gene." (PMID 32824685, 2020). "The distinctive mRNA expression pattern suggests altered cellular motility in cancer cells with IDH1 mutation." (PMID 32224866, 2020). "We demonstrated its use to effectively and comprehensively map the metabolic consequences of a specific cancer-related metabolic gene mutation (IDH1)." (PMID 32433536, 2020). "The R132H and R132C variants of the IDH1 mutations are the most observed somatic changes in human malignancies, and are identified in 91.86% of all IDH1-mutated cancers." (PMID 32825279, 2020). "Among the notable recent discoveries in cancer genome-wide sequencing was the discovery of the isocitrate dehydrogenase 1 and 2 (IDH1/2) R132H mutation." (PMID 32295632, 2020). "The oncometabolite 2-HG, generated by mutated IDH1/2, can also regulate the epigenetic program and influence cancer development." (PMID 32312982, 2020). "Isocitrate dehydrogenase 1 (IDH1) is one of the most important enzymes to be involved in cellular metabolism and can be strongly associated with the risk of cancer as well as its clinical outcome." (PMID 32110969, 2020). "Our study highlights a possible therapeutic strategy for IDH1-mutated cancers by targeting the endocytosis pathway, such as the mTORC2/Rictor/Rac1 axis." (PMID 32224866, 2020).
cancer (continued). "To investigate the impact of IDH1 mutation on cancer biology, we established IDH1 mutation (IDH1R132C and IDH1R132H)-transduced U251 cell lines." (PMID 32224866, 2020). "Despite the lack of significant differences, a correlated trend was observed for IDH1 mutation (P = .114) and family history of cancer (P = .219)." (PMID 31710183, 2020). "In summary, this study demonstrated that IDH1-mutated cancer cells exhibit increased endocytosis through activation of the mTORC2/Rictor/Rac1 axis." (PMID 32224866, 2020). "As cancer-associated mutations occur predominantly in IDH1, we mainly focus on IDH1 mutants and their impact on cancer biology." (PMID 32825279, 2020). "IDH enzymes normally produce α-ketoglutarate (αKG), however, cancer cells with mutated IDH1/2 produce 2-hydroxyglutarate (2-HG) which is detrimental to TET2, because TET2 uses αKG as a co-activator, resulting in TET2 having impaired functionality." (PMID 32781570, 2020). "Targeting Rictor, as well as its downstream molecule Rac1, suppresses IDH1-mutated cancer progression with reduced cell motility and endocytosis." (PMID 32224866, 2020). "Our study identifies common effects of IDH1/2 mutations on DNA methylation across six cancer types, derived from all three embryological layers." (PMID 31727977, 2019). "Several studies provided strong evidence for the oncogenic potential of IDH1/2 mutations, leading to the production of an oncometabolite 2-HG, which alters epigenetic regulation, cancer cell differentiation, and cell metabolism." (PMID 30857299, 2019). "In cancers with IDH1/2 mutations, 2-HG levels can reach millimolar concentrations saturating normal clearing mechanisms." (PMID 31727977, 2019). "Point mutations in IDH1, mainly at R132, are observed in a variety of cancers including low-grade gliomas, acute myeloid leukemia, myelodysplastic syndrome, and chronic myelomonocytic leukemias." (PMID 31288436, 2019). "Since the discovery of the frequent occurrence of IDH1 mutations in various types of cancer, research has mainly focused on the oncogenic effects of D-2-HG, the product of the mutant enzyme." (PMID 31139406, 2019). "Based on these backgrounds, it is becoming clear that development of therapeutic application of IDH1/2 mutant inhibitors would be useful for treatment of IDH1/2-mutated cancer." (PMID 31151327, 2019). "IDH1/2 mutations are early drivers present in diverse human cancer types arising in various tissue sites." (PMID 31727977, 2019). "This hypermethylation state caused by IDH1/2 mutations are widely present in the CpG island of the human malignant tumor genome." (PMID 31263678, 2019). "Depending on associated genomic aberrations and a cellular context, the oncogenic potential of IDH1/2 mutations ranges from an initiating event, which promotes transformation, to a secondary oncogenic event conferring selective advantage to cancer cells." (PMID 30857299, 2019). "The most common IDH mutation found in cancer is the substitution of a single arginine in the catalytic site of the enzyme, R132 in IDH1 and R140 or R172 in IDH2, which results in a gain of function." (PMID 31817761, 2019). "Lastly, we analyzed the effect of common hyper- and hypomethylated gene bodies, enhances and promoters on biologic pathways to identify biologic processes shared among all IDH1/2 mutated cancers in our study." (PMID 31727977, 2019). "Cancer genomic analyses have identified that an abnormal increase in the D-2HG level is associated with mutations in either IDH1 or IDH2." (PMID 31221981, 2019). "IDH1 mutations producing 2-HG have been found to make ICC cell lines more sensitive to an anti-cancer inhibitor of bromodomain and extraterminal domain (BET) proteins." (PMID 31795195, 2019). "2-HG is involved in the development and progression of these diseases and antibodies targeting mutated IDH1/2 in cancer can prolong survival in treated patients." (PMID 31092874, 2019).
cancer (continued). "The authors also introduced different mutations in IDH1 substrate-binding residues including the naturally occurring cancer mutation R132H." (PMID 31504662, 2019). "In vitro and in vivo preclinical studies demonstrated that inhibition of mutated IDH1/2 enzymes reduces intracellular 2-HG levels, reverses epigenetic deregulation, and releases the differentiation block in cancer cells." (PMID 30857299, 2019). "While mutated IDH1/2 genes have been thoroughly described in cancers, the significance of aberrant expression of these enzymes and their possible therapeutic implications have been partially investigated." (PMID 31010244, 2019). "IDH1 mutation is associated with increased oxidative stress with elevated ROS levels, contributing to an increased risk of cancer." (PMID 30708988, 2019). "Despite IDH1/2 mutations supposedly affecting the same enzymes in all cancers, all tumors still clustered based on their tissue of origin and more specifically the embryonal layer." (PMID 31727977, 2019). "Mutations in isocitrate dehydrogenase 1 (IDH1) occur in various types of cancer and induce metabolic alterations resulting from the neomorphic activity that causes production of D-2-hydroxyglutarate (D-2-HG) at the expense of α-ketoglutarate (α-KG) and NADPH." (PMID 31139406, 2019). "Gain-of-function mutations in isocitrate dehydroge-nase 1 (IDH1) occur in multiple types of human cancer." (PMID 29320744, 2018). "For LGG, we further adjusted for cancer subtype defined based on the IDH1 or IDH2 mutation and chromosome 1p and 19q co-deletion." (PMID 30388102, 2018). "These IDH1/2 mutations are thought to result in hypermethylated histones and DNA which in turn alters gene expression and drives cancer progression." (PMID 30405699, 2018). "While IDH1 mutations are oncogenic in other cancer types, our work highlights the importance of wild-type IDH1 in PDA pathogenesis." (PMID 30631752, 2018). "More recently, mutations in isocitrate dehydrogenase I and II (IDH1/2) in cancers have gained wide attention." (PMID 29439493, 2018). "CIMP-positive, BRAF mutant/MSS cancers were found to harbour a hotspot mutation at R132 in IDH1 which causes CIMP in glioma." (PMID 30598662, 2018). "Cancer-associated heterozygous mutations in IDH1 and IDH2 result in the formation of wild-type-mutant heterodimers with neomorphic activity, allowing the reduction of α-KG to 2-hydroxyglutarate (2HG) in the presence of NADPH." (PMID 29342092, 2018). "Our results on the interaction of TCA cycle-related metabolites with isolated KDM5B reveal the potential for its inhibition by some, but not all, of the tested compounds, including D-2HG, levels of which are elevated in cancer cells due to mutations to IDH1/2." (PMID 28827149, 2017). "While TET1 mutation is responsible for AML, the other TET2 and TET3 enzymes as well as TET enzyme cofactors (isocitrate dehydrogenases, IDH-1, and -2) were found mutated in several types of cancer and contribute to DNA methylation deregulation." (PMID 28587163, 2017). "The proliferation rate of A375 cells co-cultured with IDH1-knockdown fibroblasts was similar as co-cultured with cancer-associated fibroblasts (CAF)." (PMID 29137396, 2017). "IDH1 mutations are likely to be a direct cancer driver in early stage of gliomagenesis promoting extensive alteration of the epigenetic pattern." (PMID 28948065, 2017). "Its insufficient level in IDH1 mutated cancer cells, decreased the efficiency of this important DNA repair mechanism in them and made them vulnerable to DNA-damaging agents." (PMID 28785398, 2017).